CLVS2 (clavesin 2)
Description:
Required for normal morphology of late endosomes and/or lysosomes in neurons (By similarity). Binds phosphatidylinositol 3,5-bisphosphate (PtdIns(3,5)P2).
Synonyms: C6orf212; C6orf213; RLBP1L2; bA160A10.4
Tractability: Antibody: UniProt places it where antibodies can reach, with high confidence. PROTAC: its protein half-life has been measured.
Gene: Protein-coding gene on chromosome 6 (122,996,131 to 123,072,925, forward strand). Ensembl gene ENSG00000146352.
Subcellular location: Golgi apparatus, trans-Golgi network membrane; Cytoplasmic vesicle, clathrin-coated vesicle; Early endosome membrane
Pathways (Reactome):
Vesicle-mediated transport: Lysosome Vesicle Biogenesis
Gene Ontology:
Molecular function: phosphatidylinositol-3,5-bisphosphate binding; protein binding; phosphatidylinositol bisphosphate binding
Biological process: lysosome organization
Cellular component: endosome; clathrin-coated vesicle; trans-Golgi network; trans-Golgi network membrane; cytoplasmic vesicle; early endosome membrane; Golgi apparatus
Genetic constraint (gnomAD): Loss-of-function variants: 13 observed, 21.34 expected, observed/expected ratio (o/e) 0.61, 90% interval 0.4 to 0.97. The upper end of that interval is the gene's LOEUF score, 0.97, which puts it in group 4 of 6, group 1 being the genes least tolerant of losing a copy. Missense variants: 250 observed, 368.33 expected, observed/expected ratio (o/e) 0.68, 90% interval 0.61 to 0.75. Synonymous variants: 144 observed, 142.05 expected, observed/expected ratio (o/e) 1.01, 90% interval 0.88 to 1.16.
Homologues: Orthologues: chimpanzee CLVS2 (100% identical), dog CLVS2 (100% identical), macaque CLVS2 (100% identical), pig CLVS2 (99% identical), rabbit CLVS2 (99% identical), mouse Clvs2 (98% identical), guinea pig CLVS2 (96% identical), tropical clawed frog clvs2 (95% identical), zebrafish clvs2 (89% identical), rat Clvs2 (60% identical), Drosophila melanogaster CG33966 (24% identical), Drosophila melanogaster CG31636 (22% identical), and 10 more. Paralogues in human: CLVS1 (81% identical), TTPAL (33% identical), RLBP1 (33% identical).
Diseases named in the same sentence as CLVS2 in open-access papers:
CLVS2 is named in the same sentence as 6 diseases in open-access papers, as found by Europe PMC text mining. Sharing a sentence is not in itself a finding about the gene and the disease. The quoted sentences say what the papers report.
cognitive decline (1 paper, 2025). "In conclusion, we validated cognitive decline-related variants in the HOPE Cohort and identified novel genes associated with SCD, SEPHS2 and CLVS2, supported by multi-omics evidence." (PMID 40728933, 2025). "Furthermore, conditional analysis incorporating 22 loci associated with cognitive decline from the GWAS Catalog (selected from 455 before pruning) showed that both SEPHS2 and CLVS2 retained their original P values, indicating the robustness of our findings." (PMID 40728933, 2025). "Further investigations to validate the roles of CLVS2 and SEPHS2 may provide a more comprehensive exploration of mechanisms related to cognitive decline." (PMID 40728933, 2025).
Glucose intolerance (1 paper, 2026). Glucose intolerance (GI) can be defined as dysglycemia that comprises both prediabetes and diabetes. "The predictor variables can be considered in three groups: those with insulin and glucose intolerance (Mbd2, Tnip1, Itgb4, and Iffo2), those with BMR (1010001N08RiK and Clvs2), and those associated with Tb (Calb2)." (PMID 41432313, 2026).
neurodegenerative disease (1 paper, 2025). A disorder of the central nervous system characterized by gradual and progressive loss of neural tissue and neurologic function. "Although we identified SEPHS2 and CLVS2 as SCD-related genes, we found limited evidence indicating their association with pathways influencing neurodegenerative diseases." (PMID 40728933, 2025). "Multi-omics evidence suggests that both SEPHS2 and CLVS2 may play roles in neurodegenerative diseases." (PMID 40728933, 2025).
CLVS2 also shares sentences with these, for which no sentence is quoted: cancer (2 papers); hepatocellular carcinoma (1); liver disease (1).